MAP3K8 (mitogen-activated protein kinase kinase kinase 8)
Diseases named in the same sentence as MAP3K8 in open-access papers (continued):
Sharing a sentence is not in itself a finding about the gene and the disease.
endometrial cancer (3 papers, 2019 to 2022). Primary or metastatic malignant neoplasm involving the endometrium (mucous membrane that lines the endometrial cavity). "In the case of Ishikawa endometrial cancer cultures exposed to cisplatin, it appears that in the case of MAP3K8 and SLC7A11, the miRNAs regulating their expression act as expression suppressors at the PTGS level." (PMID 35625926, 2022).
lymph node metastasis (3 papers, 2022 to 2024). "Cytokeratin 20 (CK20) and mitogen-activated protein kinase kinase kinase 8 (MAP3K8) up-regulations were observed in MSS tumors and associated with lymph node metastasis, recurrence, and/or distant metastasis and short median survival." (PMID 38541076, 2024). "AST and Spitz melanoma presenting with lymph node metastases tend to present with MAP3K8 overexpression, indicating that presence of MAP3K8 fusions may play a role in determining prognosis of a given Spitz lesion." (PMID 35747831, 2022). "AST harboring MAP3K8 kinase rearrangements may be more prone to local lymph node metastases and regional evolution." (PMID 35747831, 2022).
myeloma (3 papers, 2015 to 2021). "In multiple myeloma, MAP3K8 activation promoted the acquisition of the M2 macrophage phenotype that promotes immunosuppression and inflammation." (PMID 35004849, 2021).
renal carcinoma (3 papers, 2019 to 2023). A carcinoma arising from the epithelium of the renal parenchyma or the renal pelvis. "Another study demonstrated that MAP3K8 induces invasion and metastasis in renal cancer cells." (PMID 32986377, 2020).
tauopathy (3 papers, 2022 to 2023). Neurodegenerative disorders involving deposition of abnormal tau protein isoforms (tau proteins) in neurons and glial cells in the brain. "AP-1 itself might be induced by MAP kinases, as suggested by the simultaneous increase in the GA of MAPK8/JNK1 and protein levels of MAP3K8/TPL-2 in (pTau +) astrocytes of both tauopathies." (PMID 35976433, 2022).
airway allergy (2 papers, 2017). "This contrasts with the role of TPL-2 in airway allergy and S. mansoni induced immunopathology where we have previously observed enhanced Th2 responses and increased serum antibody responses in Map3k8–/–mice compared to WT mice." (PMID 28759611, 2017). "Consistent with this, neutralizing Ccl24 dramatically reduced airway eosinophilia, lymphocyte infiltration, and lung inflammation in allergic mice given Map3k8−/− BMDCs, highlighting a key role of Ccl24 in mediating severe airway allergy in Map3k8−/− mice." (PMID 27484038, 2017). "Strikingly, a single adoptive transfer of HDM-pulsed Map3k8−/− DCs recapitulated many of the features of severe airway allergy, including increased airway and tissue inflammation, similar to HDM-challenged Map3k8−/− mice." (PMID 27484038, 2017). "Because various B-cell populations can regulate airway allergy, we next tested the role of B-cell–intrinsic TPL-2, using a similar mixed BM chimeric system with 80% muMT BM mixed with 20% WT or 20% Map3k8−/− BM cells transferred to Rag1−/− hosts." (PMID 27484038, 2017). "Consistent with this hypothesis, severe airway allergy induced by adoptive transfer of Map3k8−/− DCs could be blocked by neutralization of Ccl24." (PMID 27484038, 2017). "To identify how DC-intrinsic TPL-2 regulated airway allergic responses, we compared the transcriptome of ex vivo CD11c+/MHC-II+ DCs from WT and Map3k8−/− mice using a well-established model of DC-dependent HDM- mediated airway allergy." (PMID 27484038, 2017).
atherosclerosis (2 papers, 2025). A disease characterized by the build-up of fatty material and calcium deposition in the arterial wall resulting in partial or complete occlusion of the arterial lumen. "MAP3K8 also regulates the number of monocytes, which are pivotal cells in the development of atherosclerosis." (PMID 40933471, 2025). "ICAM1, MAP3K8 and TNFAIP3 are highly associated with the development of atherosclerosis." (PMID 40607379, 2025).
fungal infection (2 papers, 2017 to 2018). "A recent computational approach using publicly available transcriptome datasets for the discovery of common immunomodulators in fungal infections also pinpointed MAP3K8 and SERPINE1 in the top ten consistently perturbed gene sets." (PMID 28727728, 2017).
glioblastoma (2 papers, 2018 to 2025). The most malignant astrocytic tumor (WHO grade IV). "MAP3K8 acts as a convergence node for TNF-α and Toll-like receptor (TLR) signaling, triggering ERK and JNK cascades, both of which are implicated in glioblastoma stemness, invasion, and resistance to therapy." (PMID 40565357, 2025).
ischemic stroke (2 papers, 2021 to 2022). A stroke disorder caused by obstruction of blood flow to the brain, due to thrombotic (local blood clot formation) or embolic (due to a blood clot or other material traveling from another site) event. "A recent study showed that miR-381-3p downregulated Map3k8 to inhibit inflammation and the activation of TNF-α signaling pathway following ischemic stroke." (PMID 33986769, 2021).
liver disease (2 papers, 2014 to 2017). "Owing to its role in controlling cytokine and chemokine production during inflammatory processes, Map3k8 has been identified as a potentially interesting target for the treatment of various diseases, including autoimmune and liver diseases and diverse types of cancer." (PMID 28694430, 2017). "Map3k8 controls the production of inflammatory, M1, and M2 cytokines in immune cells, 28, 32–34 and has been identified as a potentially interesting target for the treatment of inflammatory diseases, including autoimmune and liver diseases, and diverse types of cancer." (PMID 28694430, 2017).
lung adenocarcinoma (2 papers, 2020). A carcinoma that arises from the lung and is characterized by the presence of malignant glandular epithelial cells. "We identified four biomarkers (MAP3K8, CCL20, VEGFC, and ANGPTL4) that could predict overall survival in lung adenocarcinoma (HR = 1.98, 95% CI 1.48 to 2.64, P = 4.19e−06) and this model could be used as a classifier for the evaluation of low-risk and high-risk groups." (PMID 32019546, 2020).
Sepsis (2 papers, 2015 to 2021). Sepsis is defined as life-threatening organ dysfunction caused by a dysregulated host response to infection. "MAP3K8 is linked to sepsis in mice, with being crucial for the TNF production." (PMID 25814982, 2015).
serous ovarian carcinomas (2 papers, 2015 to 2018). "Here we demonstrate that an additional MAP3K, MAP3K8 (TPL-2/COT), accumulates in high-grade serous ovarian carcinomas (HGSCs) and is a potential prognostic marker for these tumours." (PMID 26456302, 2015).
skin inflammation (2 papers, 2021). "Likewise, MAP3K8 is a key regulator of the innate immune response and is responsible for activation of extracellular signal–regulated kinase 1/2 and p38 MAPK, whose expression have been implicated in skin inflammation in response to irritants in in vivo experimental models and in reconstituted HSE." (PMID 34909715, 2021).
angiomatoid fibrous histiocytoma (1 paper, 2024). "Specifically, MAP3K8 and ALK presented PAX8+ papillary proliferations, ESWR1/FUS::ATF1 and EWSR1::YY1 displayed angiomatoid fibrous histiocytoma-like patterns, while SUFU showcased ‘tissue culture’-like spindle cell proliferation." (PMID 39059063, 2024).
astrocytic tumor (1 paper, 2025). A glial tumor of the brain or spinal cord showing astrocytic differentiation. "To investigate potential epigenetic regulation of inflammatory mediators, we analyzed the promoter methylation status of TNF-α, IL-1β, MAP3K8, and MAP2K7 in astrocytic tumors across different malignancy grades." (PMID 40565357, 2025).
astrocytomas (1 paper, 2025). "In summary, our study demonstrates that dysregulation of the TNF-α signaling axis—including upregulation of TNF-α, IL-1β, and MAP3K8—is a hallmark of high-grade astrocytomas and correlates with worse patient outcomes." (PMID 40565357, 2025). "Through comprehensive analysis-including RT-qPCR, ELISA, immunohistochemistry, methylation profiling, miRNA expression, and survival analysis, we demonstrate that TNF-α, IL-1 β, and MAP3K8 are not only upregulated in high-grade astrocytomas but also independently predict worse overall survival." (PMID 40565357, 2025).
Cerebral ischemia (1 paper, 2025). Restriction of arterial blood supply to the brain associated with insufficient oxygenation to support the metabolic requirements of the tissue. "Regarding miR-760-3p, studies have shown that it can activate the NF-kB pathway in cerebral ischemia by regulating Map3k8 and can inhibit ferroptosis by targeting CHAC1 in neurons." (PMID 40427763, 2025).
eosinophilia (1 paper, 2017). "TPL-2 inhibited Ccl24 expression in lung DCs, and blockade of Ccl24 prevented the exaggerated airway eosinophilia and lung inflammation in mice given HDM-pulsed Map3k8−/− DCs." (PMID 27484038, 2017). "Specifically, blocking Ccl24 reduced airway eosinophilia and lymphocyte recruitment in the BAL fluid of mice given Map3k8−/− BMDCs, compared with isotype-treated mice." (PMID 27484038, 2017). "Mice receiving Map3k8−/− BMDCs and challenged with HDM had significantly higher airway inflammation with increased eosinophilia and lymphocyte recruitment." (PMID 27484038, 2017).
Granuloma (1 paper, 2016). A compact, organized collection of mature mononuclear phagocytes, which may be but is not necessarily accompanied by accessory features such as necrosis. "Mice with myeloid cell-specific deletion of Map3k8 had significantly more inflammation with larger hepatic and intestinal granulomas and more severe intestinal pathology, without any appreciable change in serum LPS." (PMID 27487182, 2016).
lung neoplasm (1 paper, 2020). A benign or malignant, primary or metastatic neoplasm involving the lungs. "For instance, SF(Pkinase, Death) contains seven members (MAP3K8, MAPK3, MAPK14, MAPK1, AKT1, CHEK2, and DAPK1) that are related to lung neoplasms." (PMID 31937869, 2020).
mesothelioma (1 paper, 2024). A usually malignant and aggressive neoplasm of the mesothelium which is often associated with exposure to asbestos. "The UMAP projection showed that all ALK, NR4A3, and MAP3K8-rearranged EM formed distinct subgroups, with transcriptomic similarities based on the histology and the site of mesothelioma." (PMID 39059063, 2024).
ovarian tumours (1 paper, 2015). "Taken together, our data show that MAP3K8 differentially accumulates in ovarian tumours along with the ternary complex known to regulate its stability." (PMID 26456302, 2015). "Indeed, we clearly demonstrate that high MAP3K8 protein levels are associated with poor prognosis in HGSC, indicating that MAP3K8 favours ovarian tumour development." (PMID 26456302, 2015). "To further determine whether MAP3K8 might also affect ovarian tumour cell migration and/or invasion, we performed transwell assay experiments." (PMID 26456302, 2015). "Importantly, MAP3K8 protein levels correlate with its kinase activity and subsequent MEK/ERK/p90RSK activation, which participates in ovarian tumour growth." (PMID 26456302, 2015).
pituitary tumor (1 paper, 2020). A benign or malignant neoplasm affecting the pituitary gland. "Indeed, we found a higher expression of miR-375 in silent CTs than in functioning ones, and it has been described that MAP3K8 is a direct target gene of miR-375 in AtT-20 mouse pituitary tumor cells." (PMID 32545591, 2020).
squamous cell carcinoma (1 paper, 2021). A carcinoma arising from squamous epithelial cells. "The overexpression of MAP3K8 in murine salivary glands induced tumorigenesis of squamous cell carcinoma." (PMID 35004849, 2021).
thyroid (1 paper, 2016). "Using a kinase open reading frame (ORF) collection and a high throughput screening methodology, Johannessen and colleagues identified MAP3K8 (the gene encoding cancer osaka thyroid (COT)/TPL2), as a driver of resistance to BRAF inhibition with PLX4720." (PMID 26999821, 2016).
thyroid tumor (1 paper, 2013). A benign or malignant neoplasm affecting the thyroid gland. "The Tpl2/MAP3k8 gene was first isolated from thyroid tumors as a gene capable of inducing morphological transformation of NIH3T3 and SHOK cells." (PMID 23457529, 2013).
uterine tumors (1 paper, 2025). "We also identified MAP3K8 as being stably downregulated in uterine tumors, with its reduced expression positively correlated with favorable prognosis." (PMID 40831931, 2025).
tumor (75 papers, 2004 to 2025). "MAP3K8 is a serine/threonine kinase associated with various immunosuppressive checkpoints, chemokines, and receptors, indicating its potential role in tumor immunity." (PMID 39944684, 2025). "The enhanced expression and activity of MAP3K8 were associated with poor prognosis and implicated in tumor progression such as cell proliferation, migration, invasion, stemness, angiogenesis, epithelial-to-mesenchymal transition, and metastasis." (PMID 35004849, 2021). "MAP3K8 will be a promising diagnostic and prognostic biomarker that allows the natural course of a tumor to be predicted, distinguishing “good outcome” tumors from “poor outcome” tumors." (PMID 35004849, 2021). "In contrast, there was a significant association between MAP3K8 protein levels and clinical response to treatment, as patients exhibiting a partial response to treatment or a progressive disease preferentially harbour tumours with high MAP3K8 protein levels." (PMID 26456302, 2015). "Although MAP3K8 is considered to play a critical role in inflammation response and immune diseases, the importance of MAP3K8-driven inflammation in tumorigenesis and tumor immunity, as well as the underlying mechanisms that drive these processes, is not fully understood." (PMID 35004849, 2021). "The up-regulation of RELA, AKT1, TLR1 and RAF1 and the down-regulation of MAPK9 and MAP3K8 were determined by RT-qPCR, indicating that the enhanced anti-tumor function may associate with T cell immune response and proliferation related Toll-like receptor-Akt-NF-κB signaling pathway." (PMID 35046962, 2021). "Silencing or inhibiting MAP3K8 impaired the anti-tumor activity of 28z CAR-NK cells, while its overexpression substantially improved the function of BBz CAR-NK cells." (PMID 40033372, 2025). "In line with mRNA-level changes, protein levels of ABLIM1, FHL5, and MAP3K8 decreased progressively from normal tissue to tumor tissues, whereas TOP2A showed an opposite trend." (PMID 40831931, 2025). "MEK inhibitors markedly reduced tumor growth in high-MAP3K8 PDX models, compared with low-MAP3K8 PDX models." (PMID 37443154, 2023). "To further explore the underlying role of MAP3K8 in HCC, we analyzed the Timer database and identified the expression of MAP3K8 in tumor tissues was higher than that in normal tissues; this was further verified by immunohistochemistry and RT-qPCR." (PMID 35982895, 2022). "Taking into account the heterogeneity of the tumor, we explored the expression of MAP3K8 from the single-cell RNA-seq data." (PMID 35004849, 2021). "Over the years, MAP3K8 has been identified as a molecular linchpin that connects inflammation, tumorigenesis, and tumor immunity." (PMID 35004849, 2021). "To find the overall expression profile of MAP3K8 across all TCGA cancers, firstly, we studied the transcriptome difference of MAP3K8 between tumor and normal samples using TIMER2.0." (PMID 34567061, 2021). "In contrast, the upregulated DEGs included both caner-drivers/oncogenes, e.g. FGFR1 and MAP3K8, and tumor suppressors, e.g. SEMA3B and BTG2." (PMID 30863497, 2019). "Using quantitative phosphoproteomic analysis of these IM‐resistant cells, we have now identified significant upregulation of tumor progression locus (Tpl2), also known as cancer Osaka thyroid (COT1) kinase or Map3k8." (PMID 29485707, 2018). "A protein kinase that links MEK‐ERK and NF‐κB signaling is tumor progression locus (Tpl2), also known as cancer Osaka thyroid (COT1) or Map3k8." (PMID 29485707, 2018). "miR-509-3p, a significant regulator of the MAP3K8 oncogene was shown to be down regulated in tumor cells." (PMID 28435518, 2017). "We identified MAP3K8 as a potential miR-589-5p target; MAP3K8 is a known tumor-promoting gene in various human tumors." (PMID 27835990, 2016). "MAP3K8 is up-regulated in multiple tumor types and is closely related to tumorigenesis and/or cancer progression." (PMID 27835990, 2016).